EZH2 (enhancer of zeste 2 polycomb repressive complex 2 subunit)
Diseases named in the same sentence as EZH2 in open-access papers (continued):
Sharing a sentence is not in itself a finding about the gene and the disease.
cancer (continued). "Loss of EZH2 function impairs pancreatic regeneration and facilitates K-Ras (G12D)-driven neoplastic progression in pancreas in vivo, suggesting that EZH2 restrict cancer progression via homeostatic control of pancreatic regeneration." (PMID 28561778, 2017). "A growing number of epigenetic inhibitors are now available including EZH2 inhibitors that are in early-stage clinical trials for treatment of haematological and other cancers with EZH2 mutations or in which overexpression has been correlated with poor outcomes." (PMID 28362441, 2017). "High EZH2 expression has been associated with different types of cancer." (PMID 28427185, 2017). "As analyzed by Western Blotting, miR-24 decreased EZH2 and this alteration may cause histone methylation changes and restorations of hyper-methylated genes in cancer." (PMID 28157714, 2017). "Moreover, low EZH2 expression was independently associated with shorter PFS in patients with cancer, suggesting that EZH2 expression is a useful additional prognostic biomarker for anti-EGFR therapy." (PMID 28147317, 2017). "In addition, overexpressions of DNMT1 and EZH2 were associated with induced proliferation and aggressive metastasis behavior, resulting in poor prognosis in many cancer types." (PMID 28360411, 2017). "Since EZH2 has a dual role in epigenetic repression and signaling activation, it is interesting to investigate the consequence of gain of function EZH2 mutations towards cancer development in terms of PRC2 dependency." (PMID 28410242, 2017). "A good number of studies suggest that the over-expression of EZH2 may have a prognostic value in some types of cancer, and it has been associated with a worse prognosis and survival rate in breast and prostate tumours." (PMID 29061982, 2017). "There is increasing evidence that the chromatin modifier EZH2 is associated with cancer." (PMID 28410242, 2017). "Interestingly, both activating and inactivating mutations in EZH2 have been identified in different cancers." (PMID 27756687, 2017). "EZH2 can be used as a molecular marker for precancerous diagnosis, and EZH2 overexpression in histologically normal breast epithelium increases the risk of developing cancer." (PMID 26349457, 2016). "Although the previous study and our findings suggest that EZH2 is subjected to GSK3β control, the underlying mechanism of this regulation may differ in different cancer types." (PMID 27494834, 2016). "Other therapies for ARID1A-mutated cancers include inhibition of EZH2, PI3K, or PARP." (PMID 27737960, 2016). "EZH2 activity is up-regulated in cancer due to gain-of-function mutations, down-regulation of its suppressors, amplification of gene expression or increase of protein abundance by oncogenic pathways such as PI3K-AKT and MEK-ERK, post-transcriptional and post-translational modifications." (PMID 27793053, 2016). "Recent reports on benign breast biopsies state that the ALDH1 activity associated with enhancer of zeste 2 polycomb repressive complex 2 subunit (EZH2), a protein involved in SC renewal and carcinogenesis, is a prognostic marker for the risk of developing cancer." (PMID 26783961, 2016). "Indeed, our results show that depletion of EZH2 caused decrease in proliferation of endothelial cell, while others observed that high expression of EZH2 promotes the proliferation of many types of cancer cells." (PMID 26416763, 2016). "As a result of its having many actions, the precise mechanism by which EZH2 affects metabolic reprogramming, a hallmark of cancers, remains unclear." (PMID 27259264, 2016). "In addition, mutations in genes other than EED, SUZ12, and EZH2 with a documented effect on canonical PRC2 function are inactivated in cancer (including hematologic neoplasms)." (PMID 27242978, 2016). "EZH2 overexpression has been reported in many types of cancer and associated with poor prognosis." (PMID 27191993, 2016).
cancer (continued). "In addition, expression of DNMT1 and EZH2 were associated with induced proliferation and aggressive metastasis behavior of cancer cells resulting in poor prognosis." (PMID 27421653, 2016). "As ERCC3 could help increase the sensitivity of cancer to radiation therapy, loss of EZH2-repression of these ERCC3 targets in t-AML indicates an increased radiosensitivity." (PMID 26043758, 2015). "Also, our work verified the possibility to the development of anti-cancer agents by disrupting the association of core PRC2 components EZH2 and EED." (PMID 25944687, 2015). "However, we cannot conclude that there is a definite association between EZH2 and a specific type of carcinoma, because of the limited number of studies that were available for any one type of cancer." (PMID 25974088, 2015). "The mechanisms underlying EZH2 regulation in cancer are unclear." (PMID 25974088, 2015). "In addition, its role in the aggressiveness of PrCa has been proposed to be mediated through its interaction with the Enhancer of Zeste homolog 2 (EZH2), the over-expression of which is strongly linked to cancer progression." (PMID 26020509, 2015). "Consistent with this implication, our microarray analyses using cancer cells revealed a clear interplay of H1.2 and EZH2 in maintaining the inactive state of growth suppressive genes, as loss of EZH2 function resulted in the derepression of approximately half of the genes that are repressed by H1.2." (PMID 26581166, 2015). "EZH2 is a histone methyltransferase that is over-expressed and mutated in cancer." (PMID 25671303, 2015). "Consistent with its role as an inhibitor of cell survival and growth, DAB2IP expression is often down-regulated in several human cancers, which is frequently associated with the promoter hypermethylation or enhancer of zeste homolog 2 (EZH2)-mediated transcriptional silencing." (PMID 26336990, 2015). "Also, Ezh2 is demonstrated to be deregulated in multiple cancers, including PCa, and has been associated with PCa progression and aggressiveness." (PMID 25605014, 2015). "Thus, it is pivotal to further investigate the underlying mechanisms of how EZH2 participates in maintaining cancer stem cells and mediates multi-drug resistance." (PMID 25431950, 2014). "In addition, EZH2 promotes the epithelial–mesenchymal transition, a process that is associated with cancer progression and metastasis." (PMID 24691023, 2014). "Moreover, activating mutations and inactivating mutations of EZH2 are also associated with certain types of cancer." (PMID 25520914, 2014). "Because EZH2 is a target of miR-25, miR-26a, miR-30d, miR-101, and miR-214, downregulation of miR-25, miR-26a, miR-30d, miR-101, and miR-214 in human cancers are associated with EZH2 upregulation and malignant phenotypes." (PMID 25364765, 2014). "This implicates that endometrial EZH2 expression may be used as a screening approach to identifying high-risk subpopulation with a potential to progress to carcinoma." (PMID 25295088, 2014). "Thus, dysregulation of miRNAs appears to be one of the major causes of EZH2 overexpression in cancer." (PMID 24348513, 2013). "In addition, EZH2 promotes epithelial–mesenchymal transition, a process that is associated with cancer progression and metastasis." (PMID 24040354, 2013). "Our analysis indicates two distinct and mutually exclusive types of cancers, one associated with a gene expression pattern of EZH2 activation and tyrosine kinase signaling and the other with HDAC4 activation with increased cytokine signaling and immune cell infiltration." (PMID 24079712, 2013). "Overexpression of EZH2 has also been linked to cancer initiation and progression." (PMID 22187039, 2012). "However, EZH2 appears to have distinct biological roles in different cancer types since it is linked with more favorite prognosis in some cancers." (PMID 23300840, 2012). "EZH2 overexpression has been linked to aggressive phenotypes of certain cancers." (PMID 23300840, 2012).
cancer (continued). "As an initial step toward screening patients for cancer genotype-directed therapy, we developed a screening assay for EZH2 codon 641 mutations amenable for testing formalin-fixed clinical specimens, based on the sensitive SNaPshot single nucleotide extension technology." (PMID 22194861, 2011). "Increases in EZH2 have been reported in several types of cancer, and might be associated with the DNA methylation of polycomb target genes." (PMID 20724161, 2010). "In addition, we investigated the association of EZH2 expression with cancer specific survival (CSS) in univariate and multivariate Cox regression analyses." (PMID 20920340, 2010). "Importantly, we show that BRCA1-deficient cancer cells are selectively dependent on their elevated EZH2 levels." (PMID 19709408, 2009). "Furthermore, USP7 depletion has been associated with reduced EZH2 levels in HCT116 cancer cells." (PMID 39310812, 2024). "In addition, the mutation or overexpression of EZH2 (H3K27-methyltransferase) has been linked to cancer and several studies have demonstrated that metformin may affect EZH2 or H3K27-methylation." (PMID 37344841, 2023). "The reported metabolic exhaustion of TILs has been attributed to direct competition between TILs and cancer cells for metabolic resources and subsequent environmental stress-induced epigenome remodeling within TILs, resulting from the loss of histone methyltransferase EZH2." (PMID 37046597, 2023). "Finally, EZH2 activity in cancer is modulated by various oncogenic mutations in EZH2 and post-translational modifications of components of the PRC2 complex, which might influence the output of EZH2-targeted therapies." (PMID 37325482, 2023). "Additionally, EZH2 has been implicated in cancer stem cell biology." (PMID 36230683, 2022). "However, EZH2-activating mutations are less frequently occurred in human cancers." (PMID 35013218, 2022). "However, the effect of dual G9a and EZH2 inhibition in other cancers and the underlying mechanisms remain unclear." (PMID 35409271, 2022). "Moreover, gain-of-function or loss-of-function mutations of EZH2 frequently occur in cancers." (PMID 35269532, 2022). "Furthermore, 12 eligible studies have indicated that rs887569 and rs2302427 in EZH2 may be correlated with a decreased cancer risk." (PMID 35813302, 2022). "Moreover, laboratory data suggest that cancer cells with ARID1A loss may be sensitive to EZH2 and BET inhibitors." (PMID 35328145, 2022). "Moreover, the TCGA data reveal that the EZH2 expression was elevated in a variety of cancers and associated with poor prognosis which further suggests EZH2 expression may be a significant biomarker in NSCLC." (PMID 35912007, 2022). "Thus, this essential role of ZMYND8 in regulating the gene activator function of EZH2 might represent a viable target for the effective treatment of cancers under hypoxia or with VHL deficiency, such as ccRCC." (PMID 33593912, 2021). "Further understanding of the mechanisms underlying the epigenetic effects of EZH2 on the development, differentiation, and immune function of T cells might provide new strategies for the combined or synergistic treatment of cancer as well as other immune-related diseases." (PMID 34737746, 2021). "In addition, BRAF abnormalities are also present in EZH2 mutated cancers." (PMID 34001246, 2021). "In addition, EZH2 has been shown to be required for the proper migration of neurons into the pons during development and upregulation of EZH2 has been implicated in invasion in a variety of cancers." (PMID 32117746, 2020).
cancer (continued). "The increased expression of EZH2 in histologically normal breast epithelium is associated with higher risk of developing cancer, suggesting that EZH2 may be a potential marker for identifying preneoplastic lesions of the breast as well as a possible target for preventative intervention." (PMID 33665162, 2020). "Thus, both the under- and over-expression of EZH2 can be associated with increased cancer risk." (PMID 33732505, 2020). "Initial work in cancer suggests that bivalency may be playing a similar role in the context of cancers with activating mutations in EZH2, such as germinal centre B cell lymphomas, where H3K27me3-mediated repression of bivalent promoters results in suppression of differentiation." (PMID 30926792, 2019). "However, it was unexpected that hypermethylated genes would continue to be repressed after UHRF1 depletion, as it is well documented that UHRF1 acts as a hub to recruit multiple proteins, including DNMT1, HDAC1, G9a, and EZH2, to repress cancer-associated genes in cancer cells." (PMID 31064417, 2019). "In addition, the association between EZH2 expression and clinicopathological characteristics, and the correlation of EZH2 with ki-67 protein were assessed to identify the significance in these malignant tumors." (PMID 30120321, 2018). "However, mechanisms of de novo resistance to EZH2 inhibitors in cancers with inactivating SWI/SNF mutations are unknown." (PMID 30297712, 2018). "Moreover, it has been revealed that the cancer-predisposed hypoxic microenvironment may promote BTICs through the upregulation of EZH2 expression." (PMID 30510924, 2018). "In addition, our data demonstrated that BCL2 inhibitors alone or in combination with EZH2 inhibitors may represent therapeutic strategies for ARID1A-mutated cancers." (PMID 30297712, 2018). "However, mechanisms of de novo or acquired resistance to EZH2 inhibitors in SWI/SNF-mutated cancer are unknown." (PMID 30297712, 2018). "In addition, EZH2 gain or loss of function mutations have also been discovered in various cancer." (PMID 29556394, 2018). "Also, many gain or loss of function EZH2 mutations have been discovered in distinct cancer types." (PMID 28410242, 2017). "When considering EZH2 as a therapeutic agent, one must take into account these parameters, together with an understanding of the functional consequences of EZH2 mutations and the cancer patient’s specific cellular oncometabolome with respect to systemic inflammatory reactions." (PMID 27239242, 2016). "Thus, we speculate that there might be an association between EZH2 and some clinicopathological features of cancer." (PMID 25974088, 2015). "The association of EZH2 with the malignant phenotype of multiple solid tumors and its role as a repressor of gene targets lead to the hypothesis that EZH2 could impact specific angiogenic mechanisms of cancer angiogenesis." (PMID 25237831, 2014). "In conclusion, this study provides a basis to consider CHEESE webserver for rapid ligand-based screening to support computational foundation for the development of phytochemical-based inhibitors of EZH2 and other cancer target of relevance." (PMID 41552643, 2026). "An even more drastic situation exists in patients with epitheloid cancers treated with EZH2‐inhibitors." (PMID 40181550, 2026). "Gain-of-function mutations of EZH2 and aberrant H3K27 methylation have been linked to human cancers." (PMID 42314051, 2026). "We present here the finding that ANCR regulates EZH2 stability and, by extension, cancer of the breast cell invasion and metastasis." (PMID 41459628, 2026). "Consistently, depletion of ADAR1 dramatically enhances the sensitivity of cancer cells and tumors to EZH2 selective degraders." (PMID 41882000, 2026).
cancer (continued). "We reveal that EZH2 maintains a hyper-m6A state in cancer cells by activating a YTHDF1-mediated m6A autoregulation pathway." (PMID 41252201, 2026). "Overexpression and dysregulation of EZH2 are frequently observed in various human cancers, including breast, prostate, lung, and hematologic malignancies." (PMID 41504013, 2026). "Cancer metastasis is facilitated by EZH2, an essential regulator of epigenetic modifications and an inducer of epigenetic modifications to chromatin (EMT)." (PMID 41459628, 2026). "Despite its significance in cancer, the interplay between eccDNA and key epigenetic regulators such as EZH2 remains largely unexplored." (PMID 41744650, 2026). "Several post‐translational modifications (PTMs) control EZH2 stability, and LncRNA are thought to play essential roles in various cancers." (PMID 41459628, 2026). "Another relatively new approach to cancer treatment is the inhibition of the epigenetic modifier enhancer of zeste homolog 2 (EZH2)." (PMID 40284428, 2025). "The cancer‐suppressing genes become silenced through EZH2‐mediated histone methylation events across different cancer types." (PMID 40959208, 2025). "In several cancers, EZH2 overexpression harbors an adverse prognosis, with several EZH2 inhibitors undergoing investigation." (PMID 40075585, 2025). "The recent adoption of EZH2 inhibitors into clinical practice has motivated efforts to study EZH2 inhibitors in cancer." (PMID 40101298, 2025). "Collectively, our results indicate that USP22 is a de novo deubiquitinase of the MHC-I suppressor EZH2 in cancer cells." (PMID 41252204, 2025). "Currently, several EZH2 inhibitors, such as valemetostat tosilate (Ezharmia) and tazemetostat (Tazverik), have been approved for the treatment of cancer." (PMID 40032852, 2025). "With a growing number of research on ferroptosis, increasing evidence is believed to be provided to show the therapeutic role of EZH2 in treating human cancer." (PMID 40028035, 2025). "These strains are associated with the induction of pro-oncogenic signatures, development of polyploid giant cancer cells (PGCCs), overexpression of enhancer of zeste homologue 2 (EZH2), and enhanced epithelial-to-mesenchymal (EMT) plasticity." (PMID 41463341, 2025). "One notable advancement in cancer treatment is the development of EZH2 inhibitors, with tazemetostat being a key example that has received FDA approval for patients with both hematologic and solid tumors." (PMID 40099195, 2025). "EZH2 modulates chromatin compaction through histone modification and therefore, we evaluated this in the cancer stem cell population using the Assay of Transposase Accessible Chromatin (ATAC-seq), which allows for an assessment of chromatin accessibility." (PMID 39789291, 2025). "Analysis of human cancer tissues revealed a positive correlation of USP22 with EZH2, both of which were negatively correlated with MHC-I expression and intratumoral CD8+ T cell infiltration." (PMID 41252204, 2025). "For instance, even though EZH2 (Enhancer of zeste homolog 2) is an attractive drug target for cancers, the design of EZH2 inhibitors is constrained by diverse undesigned effects on gene expression." (PMID 40563521, 2025). "Curcumin, a component of TCM, has been shown to decrease the expression of the PRC2 subunit EZH2 in numerous cancer cells." (PMID 40271060, 2025). "Several reports have highlighted the role of EZH2 in cancer, wherein it regulates gene expression by depositing methylation marks to suppress gene expression which in turn contributes to cancer progression and metastasis." (PMID 40289112, 2025). "This study uncovers a role for mutant EZH2 in lymphomagenesis, establishing also a new method for measuring epigenetic heterogeneity and intra-chromatin connectivity in cancer cells." (PMID 40504770, 2025). "This interaction reduces m6A modification and EZH2 expression, suggesting a synergistic role of various epigenetic modifications in cancer development." (PMID 40042761, 2025).